MIR2467 (microRNA 2467)
Synonyms: hsa-mir-2467; mir-2467
Gene: MicroRNA gene on chromosome 2 (239,351,724 to 239,351,804, reverse strand). Ensembl gene ENSG00000264292.
Homologues: Orthologues: chimpanzee MIR2467 (100% identical).